NREP (neuronal regeneration related protein)
Description:
May have roles in neural function. Ectopic expression augments motility of gliomas. Also promotes axonal regeneration (By similarity). May also have functions in cellular differentiation (By similarity). Induces differentiation of fibroblast into myofibroblast and myofibroblast ameboid migration. Increases retinoic-acid regulation of lipid-droplet biogenesis (By similarity). Down-regulates the expression of TGFB1 and TGFB2 but not of TGFB3 (By similarity). May play a role in the regulation of alveolar generation.
Synonyms: C5orf13; P311; D4S114; PRO1873; PTZ17; SEZ17
Tractability: No criterion of Open Targets' tractability assessment is met for any kind of drug.
Gene: Protein-coding gene on chromosome 5 (111,662,621 to 111,997,464, reverse strand). Ensembl gene ENSG00000134986.
Subcellular location: Cytoplasm
Subcellular location (Human Protein Atlas): Vesicles
Gene Ontology:
Molecular function: protein binding
Biological process: axon regeneration; regulation of neuron differentiation; regulation of transforming growth factor beta receptor signaling pathway
Cellular component: cytoplasm
Genetic constraint (gnomAD): Loss-of-function variants: 4 observed, 4.04 expected, observed/expected ratio (o/e) 0.99, 90% interval 0.47 to 1.83. That is too few expected variants to judge how well the gene tolerates losing a copy. Missense variants: 60 observed, 53.34 expected, observed/expected ratio (o/e) 1.12, 90% interval 0.91 to 1.39. Synonymous variants: 18 observed, 19.95 expected, observed/expected ratio (o/e) 0.9, 90% interval 0.62 to 1.34.
Homologues: Orthologues: chimpanzee NREP (97% identical), macaque NREP (96% identical), guinea pig NREP (85% identical), pig NREP (82% identical), mouse Nrep (76% identical), rat Nrep (75% identical), dog NREP (74% identical), rabbit NREP (57% identical).
Diseases named in the same sentence as NREP in open-access papers:
NREP is named in the same sentence as 18 diseases in open-access papers, as found by Europe PMC text mining. Sharing a sentence is not in itself a finding about the gene and the disease. The quoted sentences say what the papers report.
glioma (4 papers, 2010 to 2023). A benign or malignant brain and spinal cord tumor that arises from glial cells (astrocytes, oligodendrocytes, ependymal cells). "NREP, which is also known as P311, promotes axonal regeneration and cellular differentiation, and ectopic expression of NREP augments the motility of glioma cells." (PMID 37238588, 2023).
gastric cancer (3 papers, 2021 to 2024). A primary or metastatic malignant neoplasm involving the stomach. "A recent study suggests EMT in gastric cancer is also induced by the overexpression of Neuronal Regeneration Related Protein (NREP) through interaction with the TGF-β1." (PMID 38562556, 2024). "So far, the function of NREP in gastric cancer has been explored, and they found that NREP promotes the growth and metastasis of gastric cancer." (PMID 38697993, 2024). "Besides that, NREP restrains cell apoptosis in BC cells, which is similar to its role in gastric cancer cell apoptosis." (PMID 38697993, 2024).
renal fibrosis (2 papers, 2015 to 2017). A final common manifestation of a wide variety of chronic kidney diseases characterized by glomerulosclerosis and tubulointerstitial fibrosis. "Nrep (neuronal regeneration-related protein), encoding an intracellular protein linked to the augmentation of TGF-β–induced renal fibrosis, within module V was active at day 14 after IRI in inner medullary tubules." (PMID 28931758, 2017).
scleroderma (2 papers, 2021 to 2025). Scleroderma is a rare autoimmune connective tissue disorder characterized by abnormal hardening of the skin and, sometimes, other organs. "In a skin tissue dataset, a fibroblast cluster expressing POSTN, ADAM12, and NREP was found to be higher in scleroderma than normal skin tissue samples." (PMID 40232153, 2025). "Mesenchymal fibroblast markers POSTN, ADAM12, COMP, and NREP were extensively expressed in scleroderma cluster 7 fibroblasts." (PMID 34140509, 2021).
breast carcinoma (1 paper, 2024). "Besides that, NREP was also upregulated in BC tumor tissues as compared with the para-carcinoma and healthy tissues (analyzed by Breast Cancer Gene-Expression Miner v4.9)." (PMID 38697993, 2024).
HCMV infection (1 paper, 2024). "We also found that NREP expression (neuronal regeneration-related protein), which was recently shown to be expressed by regenerating chicken hair cells, was reduced throughout HCMV infection." (PMID 38440980, 2024).
Intellectual disability (1 paper, 2023). "This duplication, including 6 genes such as the NREP gene implicated in neuronal functions, was considered as pathogenic and associated with intellectual disability and neuropsychiatric disorders." (PMID 37189943, 2023).
cancer (6 papers, 2021 to 2024). A tumor composed of atypical neoplastic, often pleomorphic cells that invade other tissues. "Our findings also suggested that NREP may be involved in the activation of cancer-associated fibroblasts and the epithelial–mesenchymal transition (EMT), with transforming growth factor β1 mediating both processes." (PMID 34746143, 2021). "A previous study suggested that another gene listed in our panel, NREP, was associated with poor prognosis and may be involved in the activation of cancer-associated fibroblasts and the epithelial–mesenchymal transition, with transforming growth factor β1 mediating both processes." (PMID 37296997, 2023). "The Cancer Genome Atlas-Stomach Adenocarcinoma data showed that NREP expression was higher in GC tissues than in normal tissues (P < 0.05)." (PMID 34746143, 2021).
tumor (5 papers, 2016 to 2025). "Similar to the in vitro result, the knockdown of NREP decreased tumor growth, while overexpression of NREP showed an opposite result that promotes tumor growth." (PMID 38697993, 2024). "Compared with the normal tissues, tumor tissues exhibited a significantly higher expression level of NREP in these 9 databases." (PMID 38697993, 2024). "From GEO databases (GSE3188 and GSE111259), we found that NREP is upregulated in hypoxia BC tumor cells when compared to normoxia." (PMID 38697993, 2024). "Multivariate analysis of TCGA-STAD data revealed that NREP overexpression, age, and tumor stage were related with a poor prognosis in GC (P < 0.001)." (PMID 34746143, 2021). "Subsequent TUNEL staining showed that the overexpression of NREP promoted tumor progression in GC, at least in part, by inhibiting apoptosis." (PMID 34746143, 2021). "In this work, we found that NREP is highly expressed in BC tumor tissues and cell lines." (PMID 38697993, 2024). "Accordingly, we demonstrated that aberrantly expressed NREP may play a promoting role in tumor growth and metastasis in BC by promoting cell proliferation and glycolysis." (PMID 38697993, 2024). "Finally, FAP was associated with ECM and adhesion genes (FN1, COL5A1, SPOCK1, CDH13) and regulators of migration (NREP, SEMA5A), consolidating its central role in matrix deposition and tumor invasion, as previously shown." (PMID 41198614, 2025). "The decrease of NREP and Ki67 mRNA expression, fewer NREP-positive cells and Ki67-positive cells, and an increase of red fluorescence of TUNEL images were observed in NREP silenced cells formed tumor tissues." (PMID 38697993, 2024). "To further investigate the influence of NREP overexpression on M2 macrophage abundance in GC, we established a tumor–macrophage cell co-culture model using a transwell non-contact co-culture unit." (PMID 34746143, 2021). "In comparing the 89Zr-NRep-injected group and saline-treated controls, we observed that 89Zr-NRep alone did not affect either tumour growth or survival rates." (PMID 27319780, 2016). "Our results show that NREP may act as an important player in the complex gene regulatory machinery driving GC via processes such as EMT activation, CAF activation, actin cytoskeleton remodeling, and M2 macrophage infiltration, ultimately promoting tumor development." (PMID 34746143, 2021).
NREP also shares sentences with these, for which no sentence is quoted: keloid (2 papers); adenocarcinoma (1); Gastric Tumors (1); glioblastoma (1); IgA nephropathy (1); melanoma (1); neurological diseases (1); protein misfolding disorders (1); small cell lung carcinoma (1).